TNF (tumor necrosis factor)
Diseases named in the same sentence as TNF in open-access papers (continued):
Sharing a sentence is not in itself a finding about the gene and the disease.
ankylosing spondylitis (continued). "Behçet disease, gout and ankylosing spondylitis patients, including those under anti-TNF therapy in the latter disease, do not seem to have reduced fertility whereas in dermatomyositis, the fertility potential is hampered by disease activity and by alkylating agents." (PMID 27120778, 2016). "In addition, in AS, there were associations for age at disease onset (<29 years; odds ratio (OR) = 0.222), disease severity (Bath Ankylosing Spondylitis Disease Activity Index (BASDAI) score > 4; OR = 0.152) and response to anti-TNF treatment (OR = 2.25) under a dominant model (AA + AG vs. GG)." (PMID 26019597, 2014). "Researchers have explored the potential of mAb TNF-alpha antagonists in treating conditions like sciatica, chronic low back pain (CLBP) with or without radiculopathy, and ankylosing spondylitis [112••]." (PMID 38386244, 2024). "Tumor necrosis factor-α (TNF-α) inhibitors are the main types of biological conventional synthetic disease-modifying antirheumatic drugs and have efficacy in treating ankylosing spondylitis (AS) which is not sensitive for nonsteroidal anti-inflammatory drug." (PMID 34692850, 2021).
endotoxemia (507 papers, 2004 to 2026). "Previous studies have shown that Mir221/222 expression is induced by LPS and TNF in macrophages and that they are implicated in LPS tolerance and endotoxemia." (PMID 39235454, 2024). "In this study, serum TNF-α, IL-1β, and IL-6 levels were remarkably elevated in the alcohol group, indicating that alcohol intake caused enteric-derived endotoxemia and produced large numbers of inflammatory factors." (PMID 37432394, 2023). "This is thought to be due to endotoxemia, damage associated molecular patterns (DAMPs) and induction of procalcitonin synthesis by TNF-α and IL-1β." (PMID 38435410, 2023). "In particular, the increased expression and secretion of tumor necrosis factor (TNF), associated with high endotoxemia, stimulate SREBP1c activation, one of the protagonists of DNL." (PMID 35334784, 2022). "We first found that compared to wild-type mice, Ets2-deficient mice showed higher levels of IL-6 and TNF-α after LPS challenge, indicating the crucial role of Ets2 in attenuating inflammation in mouse endotoxemia." (PMID 31785145, 2019). "We have previously reported that IAP deficiency-induced endotoxemia leads to systemic inflammation as evidenced by increased serum TNF-α." (PMID 31915470, 2019). "Our results suggest that LPS caused a significant increase in serum TNF-α and IL-6 levels in the endotoxemia model group, whereas pretreatment with ouabain significantly abolished this phenomenon." (PMID 31182997, 2019). "To study the role of α7nAChR in the persistent inhibition by VNS of TNF release in endotoxemia, we next studied α7nAChR deficient and wild type mice." (PMID 30538698, 2018). "Researches proposed LPS-induced acute liver injury, possibly derived from endotoxemia, was related to the inflammatory-associated Kupffer cells as well as inflammatory mediators including TNF-α, IL-1β, nitric oxide, and superoxide." (PMID 29861657, 2018). "TNF-α has been described to be associated with the human endotoxemia and several inflammatory disorders, and blocking of this cytokine seems to inhibit endotoxin-induced IL-1Ra release; indeed, this relationship to TNF-α has not been examined in horses." (PMID 27316332, 2016). "Weight loss is a hallmark of endotoxemia in both mammals and birds which is mediated through several pro inflammatory cytokines such as IL-1, IL-6, and TNF-α." (PMID 27463239, 2016). "A number of studies have demonstrated that cardiac dysfunction during endotoxemia is caused by inflammatory cytokines, including TNF-α, IL-1β and IL-6." (PMID 25209241, 2014). "In in vivo mice studies, propofol significantly improved myocardial depression and increased survival rate of mice after LPS treatment or during endotoxemia, which associates with reduced myocardial TNF-α production, gp91phox, ERK1/2, and p38 MAPK." (PMID 25180066, 2014). "Along with endotoxemia, ethanol feeding also increased hepatic inflammation as shown by increased hepatic TNF-α expression, and caused injury as seen by significantly increased ALT levels." (PMID 23326376, 2013). "In the present study, chronic alcohol gavage caused significant endotoxemia in rats which was markedly reduced on supplementation with catechin, thus supporting the correlation amongst endotoxin, Kupffer cells and TNF-α production." (PMID 21673994, 2011). "Second, TNF-dependent lethality in models of endotoxemia is associated with delivery of TNF to the intestinal lumen via the bile duct." (PMID 20419161, 2010). "The initial endotoxemia is followed by 24 and 48 hr TNF rise which is then followed by gradual weight loss in the infection vs. burn alone group." (PMID 16168063, 2005). "Several inflammatory mediators, derived from the host cells, are responsible for most manifestations of endotoxemia, causing an increase in the production of endogenous cytokines, such as TNF-α and IL-6, IL-8, and IL-10, which play a critical role in inflammatory responses." (PMID 38338117, 2024).
endotoxemia (continued). "Tumor necrosis factor-α (TNF-α) is also an important cytokine associated with endotoxemia." (PMID 38339007, 2024). "Of note, the HDAC inhibitor Cambinol has been shown to inhibit TNF and IL-6 secretion in bone marrow-derived macrophages stimulated with LPS and was associated with greater survival in a murine lethal endotoxemia model and in response to Klebsiella pneumoniae challenge." (PMID 34046027, 2021). "This was associated with reduced endotoxemia and TNF-α production." (PMID 33375200, 2020). "It is shown that LGG is safe and well tolerated in patients with cirrhosis and could cause reductions of the endotoxemia and TNF-α production." (PMID 30658519, 2019). "Indeed, in one case study of a patient with acute endotoxemia, ibuprofen was actually found to cause significant increases of circulating pro-inflammatory TNF-α and IL-6." (PMID 30400801, 2018). "In accordance, VDR KO mice have shown to be more susceptible to LPS-induced endotoxemia, have higher expressions of inflammatory cytokines (e.g., TNF-α, IL-1a, IL-1β, IL-10, IL-21, and IFN-γ), and experience more weight loss, bleeding, ulceration, septic shock, and death compared to wild-type mice." (PMID 28066436, 2016). "In man, this relationship has been shown during endotoxemia and high level of acute-phase protein and could be linked to the involvement of TNF-α in the course of several diseases." (PMID 27316332, 2016). "TLR4-mediated and CD40-mediated signals received by macrophages during early endotoxemia are known to promote IL-10 transcription, which can in turn signal to degrade mRNA encoding TNFα, thus identifying IL-10 as a crucial feedback control molecule that mediates cessation of inflammation." (PMID 27125280, 2016). "A previous report from our group showed that neutralization of endotoxin by endotoxin neutralizing protein attenuated acute alcohol-induced TNF-α production and liver injury, indicating a cause-effect relationship between endotoxemia and hepatic cytokine expression as well as liver injury." (PMID 26501337, 2015). "Intravenous administration of either TNF-α or IL-1β can induce a similar change to that caused by endotoxemia and endotoxic shock, and cardiovascular abnormalities, and mortality can be ameliorated by applying IL-1β receptor antagonist or anti-TNF-α antibodies." (PMID 25209241, 2014). "Interestingly, IL-10 knockout mice exhibit unregulated inflammatory activity exemplified by enhanced TNF-α accumulation, which is associated with a variety of pathogenic outcomes, including endotoxemia and intestinal inflammation." (PMID 19040745, 2008). "Neutropenia is associated with the production or regulation of TNF-α in endotoxemia." (PMID 17397554, 2007). "A fanatical production of proinflammatory cytokines such as TNF produced during endotoxemia may cause organ injury or eventual death, even though TNF may be required in healing the damaged tissues caused by infection or injury in the early stage or mild inflammatory response." (PMID 20628562, 2010). "Greater intestinal permeability contributes to endotoxemia, elevated circulating pro-inflammatory factors (e.g., IL-6, TNF-α) and systemic low-grade inflammation." (PMID 41602079, 2026). "In a murine model of lipopolysaccharide (LPS)-induced endotoxemia, abdominal ultrasound significantly reduced plasma TNF-α levels." (PMID 41671184, 2026). "In mice with severe endotoxemia, serum interleukin-6 (IL-6) and tumor necrosis factor-α (TNF-α) levels were significantly reduced in DMA-treated animals compared with lipopolysaccharide (LPS)-only controls." (PMID 42001814, 2026). "Both, UDCA and CDCA pretreatment given orally for 10 days exerted anti-inflammatory effects manifested by a significant decrease in the levels of TNF-α, GM-CSF, and IL-1β in the LPS-induced endotoxemia." (PMID 38578526, 2025). "Anti-inflammatory finding agrees with previous work that showed ertugliflozin significantly decreased IL-6 and TNF-a levels in mice exposed to endotoxemia." (PMID 41341617, 2025).
endotoxemia (continued). "In a rat endotoxemia model, fluoxetine treatment protected from elevated circulating levels of the pro-inflammatory cytokines tumor necrosis factor–α (TNFα), IL-6, and IL-1β." (PMID 39951524, 2025). "A recent study demonstrated that SD attenuates the production of tumor necrosis factor in the spleen and serum of mice with endotoxemia." (PMID 40835804, 2025). "Several studies have shown that L. lactis can attenuate LPS-induced endotoxemia by reducing proinflammatory cytokines such as TNF-α and IL-6, preserving intestinal integrity, and limiting microbial translocation." (PMID 40964057, 2025). "It resulted in the reduction of endotoxemia (through LPSs) and pro-inflammatory cytokine (TNF-α, IL-6, and IL-1β) levels, with the increased expression of tight-junction associated proteins (claudin-1, occludin, and zonula occludens-1)." (PMID 41334341, 2025). "The in vivo efficacy of P12 in LPS‐induced endotoxemia showed a significant reduction in serum IL‐6 and TNF‐α." (PMID 40599085, 2025). "In murine models of endotoxemia, PI treatment reduced TNF-α synthesis, supporting its anti-inflammatory potential, consistent with human data showing that FMT reduces inflammatory markers." (PMID 41303703, 2025). "The effects of endotoxemia on the hypoxic mouse brain have been reported to induce exacerbation of inflammatory mediators IL-1β, IL-6, and TNF-α." (PMID 39940901, 2025). "Similar effects were observed as AFK-PD ameliorated lethal endotoxemia in mice by inhibiting the production of TNF-α and IL-1β in M1 macrophages." (PMID 39268467, 2024). "Studies have shown that endotoxemia induces intestinal mucosal injury as well as chronic inflammatory bowel disease by upregulating TNF-α expression." (PMID 39555553, 2024). "When endotoxemia causes ALI, pro-inflammatory cytokines such as IL-1β and TNF-α are expressed by the neutrophils that migrate into the airways and infiltrate the lungs." (PMID 40007534, 2024). "The study used TNF-α (50 ng/ml) combined with LPS (1 μg/ml) to stimulate H9C2 cells for 6 h to mimic the inflammatory hyper-responsive state of early endotoxemia." (PMID 38784400, 2024). "In this study, there was a clear increase, over time, in TNF-α, IL-6, and IL-10 in both experimental groups, which is characteristic and consistent with the correct induction of endotoxemia." (PMID 38338117, 2024). "We also analyzed cytokine levels in plasma and detected a strong release of tumor necrosis factor, interleukin-6 (IL-6), monocyte chemoattractant protein-1, and IL-10 48 h after endotoxemia." (PMID 38984201, 2024). "In animal models of endotoxemia, carnitine treatment has been demonstrated to reduce circulation levels of tumor necrosis factor (TNF)-α and boost survival rates." (PMID 39274215, 2024). "In the study for microglia activation, we used TNFα, which level increases rapidly in the blood during endotoxemia." (PMID 39456170, 2024). "To study the effects of capsaicin on endotoxemia and systemic inflammation, we measured serum levels of LPS, TNF-α, and IL-6." (PMID 39201665, 2024). "In particular, an intraperitoneal LPS injection in huNSG-QUAD mice resulted in similar serum levels of human TNF, IL-6, IL-8 and IL-1β in an analogous systemic endotoxemia experiment." (PMID 39399507, 2024). "Particularly, after endotoxemia, animals with obstructive jaundice often exhibit more intense systemic and pulmonary production of TNF-α and IL-6, as well as increased accumulation and activation of inflammatory cells." (PMID 39744639, 2024). "Cmtm3 KO alleviated the release of TNF-α, IL-1β, and IL-10 in the peripheral blood of LPS-induced endotoxemia mice, while TLR4 overexpression reversed this alleviating effect." (PMID 39455728, 2024). "For example, a recombinant 53 kDa glycoprotein from TsES (rTsP53) displays anti-inflammatory characteristics and protects mice from endotoxemia induced by lipopolysaccharides (LPS) by reducing levels of pro-inflammatory agents (TNF-α, IL-1β, and IL-6)." (PMID 38727220, 2024).
endotoxemia (continued). "The serum concentration of TNF-α rises 15 to 30 min after the induction of endotoxemia, reaching a maximum peak of around 60 to 90 min." (PMID 38338117, 2024). "As the early mediators of endotoxemia, IL-1β and TNFα mainly released by macrophages from the injured site into circulation cause septic shock and multiple organ injuries." (PMID 36776867, 2023). "CYP2E1-mediated ROS can also stimulate endotoxemia and elevate serum levels of LPS, which can travel to the liver, upregulating pro-inflammatory mediators, including tumor necrosis factor-alpha (TNF-α) and hypoxia-inducible factor 1-alpha (HIF1-α)." (PMID 38247468, 2023). "Optogenetic stimulation of DMN cholinergic neurons has been shown to be protective during endotoxemia by reducing TNF production." (PMID 37180135, 2023). "Endotoxemia in mouse models resulted in an exponential increase in plasma TNF-α and IL-6 levels for up to 20 h18." (PMID 38040923, 2023). "The magnitude of the signal during SpNS is inversely correlated with subsequent TNF suppression in endotoxemia and explains 40% of the variance in TNF measurements." (PMID 37848937, 2023). "CYP2E1-mediated oxidative stress can also sensitize the liver to toxicity via endotoxemia and intestinal TNF-α via a CYP2E1-thioredoxin-ASK1-JNK1 pathway." (PMID 38247468, 2023). "Crucially, mice lacking CTRP6 had attenuated systemic inflammation in response to endotoxemia, as indicated by reduced serum TNF-α and attenuated LPS-induced hypothermia." (PMID 38103643, 2023). "The inflammatory response to LPS was validated by the substantial increments in circulating TNFα and IL-1β, two key proinflammatory cytokines that characterize the early immune response to endotoxemia." (PMID 37180728, 2023). "Together, these data establish that vagus TRPA1+ nociceptors are necessary and sufficient to stimulate a reflex anti-inflammatory response via afferent vagus nerve fiber signaling and inhibit TNF production during endotoxemia." (PMID 36650454, 2023). "For example, administering VNS with the splanchnic nerve sectioned abolishes the TNF-lowering effect of stimulation in a model of LPS endotoxemia." (PMID 37848937, 2023). "By inhibiting the NF-κB signaling pathway, MLT reduces the synthesis of IL-1β, TNF-α, and NO, which are involved in developing inflammation in endotoxemia." (PMID 38203627, 2023). "Our results show a strong correlation between early TNFα production, metabolic acidosis, and kidney injury in lethal endotoxemia." (PMID 37520526, 2023). "In a rodent model of endotoxemia, we demonstrated that an anti-inflammatory reflex mediated by the splanchnic sympathetic nerves strongly suppresses tumor necrosis factor alpha (TNF-α) response, within 1.5-h of lipopolysaccharide treatment." (PMID 37535121, 2023). "The transfer of SUMO1-null, but not wild-type, splenocytes into splenectomized wild-type mice exacerbated TNFα production and metabolic acidosis in endotoxemia." (PMID 37520526, 2023). "It is well-documented that intestinal ischemia can lead to endotoxemia, igniting an inflammatory response and bolstering TNF-α synthesis." (PMID 37960219, 2023). "Both EA of the auricular concha and vagus nerve can increase serum TNF-α and IL-6 levels, and downregulate pulmonary NF-κB p65 expression levels in endotoxemia, with similar cholinergic anti-inflammatory mechanisms." (PMID 37753078, 2023). "Methyl palmitate ameliorated histopathological abnormalities and decreased plasma levels of tumor necrosis factor alpha and interleukin 6 in rats with endotoxemia produced by lipopolysaccharide (LPS)." (PMID 37765393, 2023). "One explanation is that MRP8/14, which serves as a damage-associated molecular pattern, enhances the production of proinflammatory cytokines, such as TNF-α, to mediate lethal endotoxemia." (PMID 37701855, 2023). "TNF-α levels increase in response to stimuli such as endotoxemia, DAMPS or PAMPS-mediated receptor activation, oxidative stress, and complement activation." (PMID 38201260, 2023).